STAT3 (signal transducer and activator of transcription 3)
Diseases named in the same sentence as STAT3 in open-access papers (continued):
Sharing a sentence is not in itself a finding about the gene and the disease.
tumor (continued). "In contrast, inhibiting JAK/STAT3 signaling did not significantly affect the efficiencies of tumor formation, although the tumor latency was slightly altered compared with the vehicle-treated controls." (PMID 36982542, 2023). "In addition to STAT3, constitutive activation of STAT1 and STAT5 was also shown in tumor cells and tumor tissues." (PMID 36911202, 2023). "Mechanistically, Hsp110 could enhance the Wnt/β-catenin pathway, directly bind to the signal transducer and activator of transcription 3 (STAT3) to enhance its phosphorylation, thus contributing to tumor growth." (PMID 37978368, 2023). "The complex tumor microenvironment of GBM results in no significant improvement in patient survival as most of the patients only received administration of STAT3 inhibitors." (PMID 36923251, 2023). "Of note, the expression of total STAT3 was not significantly changed upon the addition of tumor cell CM." (PMID 36922898, 2023). "The proposed mechanism involves Candida albicans promoting the enhancement of glycolysis in macrophages, which leads to increased IL-7 secretion, thereby triggering aryl hydrocarbon receptors and STAT3 to induce RORγt+ innate lymphoid cells ILC3 to produce IL-22, promoting tumor progression." (PMID 38169837, 2023). "Furthermore, CAFs can trigger trastuzumab resistance by expanding tumor stem cells and activating multiple pathways, such as NF-κB, JAK/STAT3, and PI3K/AKT." (PMID 38001753, 2023). "Given that Wnt5a can promote tumor cell EMT and metastasis by activating the STAT3 signaling pathway, we next investigated whether TCAF2 in TPCs enhanced CRC cell motility and EMT through the Wnt5a/STAT3 signaling pathway." (PMID 37635201, 2023). "To delve deeper into the intricate interplay between PRMT6 and STAT3 R729 methylation in the context of tumor metastasis, we engineered MDA-MB-468 cancer cells to stably express various combinations: STAT3 WT+ vector, STAT3 WT + PRMT6, STAT3 R729K+ vector, and STAT3 R729K + PRMT6." (PMID 37813837, 2023). "Stattic is a potent STAT3 inhibitor for tumor treatment, but its antimicrobial activity has not yet been reported." (PMID 38032177, 2023). "As a transcriptional regulator of several tumor-promoting factors, signal transducer and activator of transcription 3 (STAT3) is involved in multiple oncogenic signaling pathways and is constitutively activated in cancer and immune cells in the tumor microenvironment." (PMID 37630387, 2023). "One potential reason for their limited efficacy is that multiple cytokines that can activate STAT3 (including OSM and LIF) may be present both in the tumor microenvironment and systemically, and blocking only one may have limited effects." (PMID 38022653, 2023). "Thus, our findings emphasize the need to better identify the roles of STAT3 and its cross-talks with other transcription factors in each specific malignancy, in different TME settings and time points along tumor progression." (PMID 37190183, 2023). "Our study revealed that inhibiting YAP expression could hinder tumor growth and macrophages M2‐type polarization, activate Treg cells, activate CD4+ and CD8+ T cells, and regulate the expression of YAP, STAT3, p‐STAT3, PD‐L1, VEGF, and VEGFR‐2." (PMID 37329188, 2023). "Meanwhile, several preclinical studies also revealed that incomplete ablation could promote tumor progression and tumor angiogenesis via the IL-6/HGF/c-Met pathway, the HGF/c-Met/STAT3 pathway, and the upregulation of VEGF." (PMID 36831664, 2023). "For unclear reasons, 2 recipients given 40 × 106 ALL cells with STAT3–/– donor T cells died without apparent tumor growth." (PMID 37526084, 2023). "In vitro experiments showed that culturing BLCA cells with medium culturing M2-type macrophages resulted in activation of the TLR4/STAT3 signaling pathway in BLCA cells, increased expression levels of EMT markers, and enhanced metastatic ability of tumor cells." (PMID 37118734, 2023).
tumor (continued). "Silibinin (SL), a bimodal Src homology-2 domain and DNA-binding domain-targeting inhibitor of STAT3, has also shown regulation of EMT and inhibition of angiogenesis, which would be beneficial to comprehensively regulate the tumor microenvironment (TME) against metastasis." (PMID 37403048, 2023). "Also, phosphorylated STAT3 leads to the upregulation and overproduction of intercellular adhesion molecule 1 (ICAM 1), contributing to tumor migration and invasion." (PMID 38067351, 2023). "The overall effect is to promote tumor progression, as M1-like macrophages could cascade a stem-like phenotype of tumor cells via the IL6/Stat3/THBS1 feedback loop." (PMID 36614179, 2023). "STAT3, a member of signal transducer and growth factors (STAT), is one of the main transcription factors that transmit the signals of several cytokines, particularly IL-6 in KRAS-mutant tumor cells." (PMID 36899885, 2023). "Altogether, Quercetin could inhibit the viability and proliferation of BC cells through Stat3, thus exhibiting the vitality of Stat3 in the signaling pathway of 14,15-EET to promote tumor cell growth." (PMID 37710176, 2023). "Likewise, the differences in the expression levels of STAT2, STAT3, STAT4, STAT5A, STAT5B, and STAT6 between normal and tumor tissues were also displayed." (PMID 36968603, 2023). "In addition, it was known that the phosphorylation of Akt1 and STAT3 regulates the transcription of HIF-1α, a core molecule that induces tumor angiogenesis." (PMID 36647454, 2023). "Besides directly promoting tumor cell proliferation, EGFR can also serve as a modulator for tumor immune monitoring, promoting the PD-L1 expression by activating the JAK/STAT3 signaling pathway, inducing T cell apoptosis and immune escape." (PMID 37799727, 2023). "However, there was an increased presence of tumour buds and higher tumour stroma percentage (TSP) detected in triple negative patients with high stromal STAT3." (PMID 37199043, 2023). "The connection between S1PR1 and STAT3 activation was fundamental in lymphoma, adenocarcinoma, melanoma, breast, and prostate cancers, and targeting S1PR1 to decrease expression of STAT3-regulated genes resulted in inhibition of tumor progression." (PMID 36672428, 2023). "It was observed that phosphorylated (activated) STAT3 expression, the indication of JAK/STAT3 signaling activity, was elevated in the CSCs when the cells were transwell cocultured with PDX tumor stromal cells in comparation with mouse normal thyroid tissue stromal cells." (PMID 36982542, 2023). "Finally, in the cancer cells of LUAD tumor samples, the KDF1 level was observed to correlate positively with the level of p-STAT3." (PMID 38137415, 2023). "Similarly, due to its effective suppression of tumor growth in murine HCC models, OPB-31121, a potent STAT3 inhibitor, was administered to 23 patients with progressive HCC at varying doses." (PMID 37762066, 2023). "STAT1 or STAT3 knockdown by siRNA reduces cytokine-induced expression, but not constitutive PD-L1 expression in human monocytes and tumor cells." (PMID 38022653, 2023). "In addition, STAT3 activity (phospho-STAT3 Tyr705) was dramatically reduced, while the expression of TUNEL-positive cells was significantly amplified by radotinib in the tumor tissue." (PMID 35503759, 2022). "An inhibitor of STAT3, WP1066, has been recently shown to have anti-tumor activity in histone H3 G34R-mutant HGG, a subtype of HGG most commonly occurring in teenage and young adult patients, and is currently being evaluated in clinical trials (NCT01904123 and NCT04334863)." (PMID 36186781, 2022). "As EPP suppressed the STAT3 and MET/AKT pathways, which stimulate tumor growth and confer EGFR TKI resistance, EPP could be applied not only to EGFR TKI-naïve or -sensitive NSCLC, but also to EGFR TKI-resistant NSCLC." (PMID 35408753, 2022).
tumor (continued). "In addition, STAT3 inhibitors, including stattic and napabucasin, suppressed STAT3 phosphorylation and activation in IL20RB-expressing tumor cells after stimulation by osteoclastic CM or IL-19, leading to inhibition of organoid formation." (PMID 36006737, 2022). "Consequently, BMX inhibition by ibrutinib specifically disrupts GSCs and suppresses GBM tumor growth, while exhibiting minimal effects on neural progenitor cells activating JAK2-mediated STAT3." (PMID 35740330, 2022). "In terms of promoting tumor drug resistance, TA-MSCs, TA-MSCs-EVs and MIF can promote tumor drug resistance by activating the same signaling pathway and regulating similar related protein expression, such as STAT3, MAPK, Bcl etc." (PMID 35842634, 2022). "LIF is aberrantly secreted by tumour cells and promotes tumour progression in pancreatic and other solid tumours through aberrant activation of the LIF receptor (LIFR) and downstream signalling that involves the JAK1/STAT3 pathway." (PMID 36359879, 2022). "In primary IBC tumor specimens and corresponding cell lines excessive IL-6 expression is a recurring feature, which correlates with positivity for the activated and phosphorylated forms of JAK2 (pJAK2) and STAT3 (pSTAT3)." (PMID 35565421, 2022). "Tumor-derived IL-6 phosphorylates STAT3 and stimulates two noncanonical NF-kB subunits, p52 and RelB to form a dimer that directly binds to the promoter of IDO1, then drives the expression of IDO1 in MDSCs." (PMID 35681736, 2022). "In addition, a sustained activation of STAT3 occurs in more than 50% of NSCLC patients, and its increased expression leads to low-grade tumor differentiation, lymph node metastasis, clinical stage progression, and drug resistance." (PMID 36010693, 2022). "In conclusion, chiauranib may be a potential therapy to treat t-FL, since it inhibits tumor growth and migration and induces apoptosis by altering the VEGFR2/ERK/STAT3 signaling pathway." (PMID 36678513, 2022). "Consequently, the pathway is like a bridge to connect tumor and TAMs, and TAMs have been proved to be involved in many pathways important to CRC,namely, NFKB1 pathway, STAT3 pathway, WNT5A pathway, and PI3K pathway." (PMID 35186730, 2022). "Furthermore, OCLN overexpression enhanced the activity of the IL8/STAT3 signalling pathway by activating STAT4, ultimately contributing to tumour vascular remodelling and metastasis." (PMID 35224833, 2022). "STAT3 directly binds to the promoter of hypoxia-inducible factor (HIF)-1α to promote gene expression; HIF-1 α in turn induces the expression of vascular endothelial growth factor (VEGF) and promotes tumor angiogenesis." (PMID 35211406, 2022). "In vivo tumor xenograft experiments showed that knockdown of circZFR inhibited tumor growth and weakened DDP resistance, while CAFs-derived exosomes incubation increased the expression of circZFR, inhibited the STAT3/NF-κB pathway, promoted tumor growth, and enhanced DDP resistance." (PMID 35139763, 2022). "The combination treatment effectively delayed tumor growth and blocked EGFR by decreasing the phosphorylation of STAT3, p38 MAPK, ERK1/2, and BAD proteins, while the IC50 value of CHE was between HCC827 (IC50=5.0 ± 0.48 μM), SK-MES-1 (IC50=6.35 ± 1.26 μM), and A459 (IC50=7.78 ± 0.56 μM)." (PMID 35721116, 2022). "Knockdown of LOXL3 can upregulate the expression of proliferation-related genes, such as cell cycle protein D1 (CCND1), in a STAT3-dependent manner, thus the overexpression of LOXL3 in HCC cells can significantly delay the cell cycle and inhibit the growth of tumor cells." (PMID 36293126, 2022). "When EVsMMA-MRC5 were collected from fibroblasts that were co-treated with antioxidants, they were no longer able to activate IL-6/JAK/STAT3 or TGFβ signaling in A549 tumor cells." (PMID 36266345, 2022). "Interestingly, adiponectin can inhibit tumor growth by either activating JNK-mediated mitochondrial apoptosis and caspases, or suppressing Akt and STAT3." (PMID 36612019, 2022).
tumor (continued). "M1‐like macrophages may inhibit HCC development by changing tumor microenvironment, and M2‐like macrophages can promote HCC cell proliferation and invasion through activating TLR4/STAT3 signaling pathway." (PMID 34850589, 2022). "STAT3 has also been reported to participate in and activate IL8‐regulated tumour angiogenesis." (PMID 35224833, 2022). "In bidirectional communication, brain endothelial cells release EVs containing tetraspanin CD9 to GBM, enhancing tumor progression through the inhibition of ubiquitination of IL6 receptor gp30 and promoting the activation of the signal transducer and activator of transcription 3 (STAT3)." (PMID 36361947, 2022). "The analysis of the GEPIA dataset and IHC in this study showed that the expression level of STAT3 in CRC was not different from that in adjacent normal tissues, but was associated with the tumor stage of patients with CRC." (PMID 36061181, 2022). "We demonstrate that CCL4 promotes Angpt2 expression in OSCC by activating signal transducer and activator of transcription 3 (STAT3) and mitogen-activated protein kinase kinase (MEK), signal-regulated kinase 1/2 (ERK) signaling, which subsequently enhances Angpt2-induced tumor angiogenesis." (PMID 35884919, 2022). "In addition to pro-tumorigenic stimuli, STAT3 activation induces immunosuppression in the TME due to reduced expression and secretion of pro-inflammatory cytokines such as IL-12 and TNF-α by tumor cells." (PMID 35267626, 2022). "However, inhibition of miR-21 significantly reduces the polarization of M2 GAMs and decreases levels of VEGF, TGF-β1, and IL-6 by decreasing activities of Sox2, PDCD4, and STAT3, ultimately inhibiting GBM tumor cell growth." (PMID 35572545, 2022). "Thus, effective control of the expression of JAK/STAT3 and PI3K/AKT by EGFR contributes to the regulation of the growth and apoptotic state of tumor cells." (PMID 35190747, 2022). "All these results supported that β-Ele combined with cisplatin effectively inhibited the tumor growth and induced apoptosis maybe by inhibiting JAK/STAT3 signaling pathway in vivo." (PMID 35909161, 2022). "From the analysis of cellular protein and tumor tissue protein by Western Blot and immunohistochemistry, it could be illustrated that Rh4 dramatically inhibited the expression of JAK2, STAT3 and p-STAT3, blocking the EMT procedure in LAC cells." (PMID 35216134, 2022). "It was found that exosomes from hypoxic culturing ovarian cancer cell lines carried more potent oncogenic proteins-STAT3 and FAS, and significantly increased cell migration, invasion, and chemo-resistance in vitro and promoted tumor progression, metastasis in vivo." (PMID 35444652, 2022). "STAT3 silencing also could reduce the expressions of cytokines IL-6, IL-1β and inflammatory mediators ICAM1 and COX2 in the tumor microenvironment." (PMID 35513871, 2022). "Data from a syngeneic tumor model with CD4+ T cell-specific ablation of S1PR1 indicate that S1PR1 on CD4+ T cells regulates intratumoral Treg expansion leading to CD8+ T cell suppression and tumor progression through STAT3-dependent activation of Tregs." (PMID 35163211, 2022). "The STAT3 inhibitor compound (Stattic) was an SH2-domain inhibitor discovered by a high-throughput chemical library screen, and Stattic significantly attenuated EZH2 expression and local tumor invasion and outgrowth via targeting STAT3." (PMID 36231093, 2022). "Moreover, increased features of NF activation noted in 4T1 tumor-bearing mice, which were the most visible in the 100 IU+cal group, may also be an effect of the increased tumor tissue concentration of IL-6, a cytokine that may activate fibroblasts through the induction of STAT3 phosphorylation." (PMID 36230508, 2022). "Moreover, ALA inhibited tumor growth in vivo, and the inhibition of AKR1C1 and STAT3 activation were also found in the murine xenograft model." (PMID 35370661, 2022).
tumor (continued). "Suppressing STAT3 signals may also induce the polarization of anti-tumoral M1 macrophages and reshape the HCC tumor microenvironment." (PMID 36232407, 2022). "Taken together, our in vitro and in vivo data using miR-155–KO tumor cells further confirms the antitumor role of endogenous miR-155 in regulating antitumor immune response by targeting SOCS1 and altering its downstream p-STAT1/p-STAT3 balance." (PMID 35925680, 2022). "The decrease in tumor growth and the expression of SREBP2 by ENSA silencing could be abolished by ectopic STAT3 expression, which confirmed the central role of STAT3 in cholesterol biosynthesis in TNBC." (PMID 35145111, 2022). "Additionally, the IHC staining of the tumor sections showed the tumors from the combination therapy group had the lowest expression levels of ACSL1, STAT3, p-STAT3, and Ki-67." (PMID 35574370, 2022). "In addition, STAT3 inhibits the expression of CXC-chemokine ligand 10 (CXCL10), which can significantly enhance NK cell cytotoxicity against tumor cells." (PMID 36557902, 2022). "STAT3 and EGR1 signaling govern T cell-mediated cell-in-cell tumor formation." (PMID 36124553, 2022). "Therefore, it can be concluded that combination of CTLA-4 blockade with MUC1 mRNA nanovaccine enhances anti-tumor cytotoxic T-lymphocyte activity by reducing immunosuppressive TME and inhibiting tumor-promoting STAT3 signaling pathway." (PMID 34875483, 2022). "Prior work from our group and others have revealed that inflammatory CAF (iCAF)-derived IL-6 engages in tumor-permissive crosstalk by activating STAT3 signaling with tumor cells, and that the CAF-tumor cell IL-6/STAT-3 signaling axis is a central mediator of chemoresistance in PDAC." (PMID 36107485, 2022). "Subsequently, macrophage-derived IL-6 activates STAT3 signaling and promotes EMT in tumor cells." (PMID 36071472, 2022). "Interestingly, the IL-6 signal loop on a self-sustaining IL-6/STAT3/AHR axis is one of the mechanisms that maintain the constitutive expression of the indoleamine 2,3-dioxygenase (IDO) enzyme in tumor cells." (PMID 36405719, 2022). "STAT3 signaling in Tregs can upregulate the expression of TGF-β and IL-10, which conversely restrain IFN-γ production by CD8+ T cells, and finally inhibit the tumor-killing activity of CD8+ T cells." (PMID 34875483, 2022). "Notably, RT was able to prevent the elevation of some important proteolytic transcriptional factors (p-STAT3, FoXO1, FoXO3) and key proteins in UPS and autophagy pathways, conferring protection against muscle wasting in tumor-bearing mice." (PMID 35847939, 2022). "Moreover, IL-6 knockdown by siRNA technology in HEp-2-CSCs decreased not only IL-6 expression levels, but STAT3 and HIF1 as well, leading to the suppression of LSCC proliferation, colony formation, invasion, and tumor growth, and inducing apoptotic cell death." (PMID 35406495, 2022). "We found that IL-6 induced STAT1 transcriptional activity upon STAT3 depletion, suggesting that HCC tumor cells may activate both STAT1 and STAT3 signaling under pro-inflammatory conditions." (PMID 35267462, 2022). "Together, Phd2 deficiency in hematopoietic cells (including TAMs), but importantly not in IECs, promotes CAC tumor growth at least in part by activation of the STAT3 and ERK1/2 signaling pathways mediated by EREG." (PMID 36509284, 2022). "Dihydroartemisinin-dependent inhibition of STAT3 decreased the levels of antiapoptotic (Bcl-xL, Mcl-1), proproliferative (cyclin D1), prometastatic (MMP-2/9) and proangiogenic (VEGF) proteins resulting in inhibited xenograft tumor growth." (PMID 36700235, 2022). "The overexpression or constitutive activation of STAT3 promotes tumor cell proliferation, which is independent of CUEDC2." (PMID 36231027, 2022). "However, the specificity of RNF7 knockdown, the effects on STAT3 activity, and a triple combination therapy of sunitinib, STAT3 inhibition, and RNF7 knockdown on regulating tumor growth in vivo need to be investigated further." (PMID 35562668, 2022).